NEDD4L (NEDD4 like E3 ubiquitin protein ligase)
Diseases named in the same sentence as NEDD4L in open-access papers (continued):
Sharing a sentence is not in itself a finding about the gene and the disease.
tumor (continued). "Elevated NEDD4L expression correlated with reduced immune cell proportions, suggesting compromised immune surveillance that may facilitate tumor progression." (PMID 41561975, 2025). "Although a tumor is a somatic disease, HECT mutations might be a novel mechanism for the downregulation of NEDD4L expression in ccRCC and also deserve further exploration." (PMID 39596003, 2024). "This tumor suppressor role of Nedd4l may explain its function in the maintenance of MuSC quiescence." (PMID 39015146, 2024). "Changes in tumour resistance to radiation were analysed in mice underexpressing NEDD4L and KLF5." (PMID 39317954, 2024). "CircNEIL3 inhibits tumour metastasis by recruiting the E3 ubiquitin ligase Nedd4L to degrade YBX1." (PMID 38378679, 2024). "Compared with their WT littermates, we found higher levels of Ki67+ cells per crypt in the adjacent tumor and tumor tissues from Nedd4l+/– and Nedd4lfl/fl VillinCre mice following AOM/DSS treatment, as well as increased lipid peroxidation production in tumor tissues of Nedd4lfl/fl VillinCre mice." (PMID 39688910, 2024). "Based on such results, it was hypothesized that NEDD4L is a tumor suppressor of CRC and that NEDD4L inhibits classical WNT signaling by targeting disheveled segment polarity protein 2 (DVL 2) for proteasomal degradation so as to inhibit tumor proliferation." (PMID 38785984, 2024). "Interestingly, the authors also found that NEDD4L exerted its tumor-suppressive effect by targeting CTR to mediate its ubiquitination degradation so as to inhibit the CTR1-AKT signaling pathway." (PMID 38785984, 2024). "Recently, more and more studies have focused on the role of NEDD4L in tumor pathogenesis." (PMID 39596003, 2024). "We next evaluated the effect of NEDD4L-mediated RAC2 ubiquitination on tumor cell growth." (PMID 39596003, 2024). "Integrated bioinformatics data suggested the role of NEDD4L as a tumor suppressor in ccRCC." (PMID 39596003, 2024). "A pan-cancer analysis showed that E3 ubiquitin ligase NEDD4L was lower expressed in ccRCC tissues, and NEDD4L may suppress tumor cell proliferation and migration by inhibiting ERBB3 and MAPK signaling pathways." (PMID 38777825, 2024). "We hypothesize that in quiescent MuSCs, Nedd4L would act as a tumor suppressor and inhibit the MuSCs ability to enter the cell cycle." (PMID 39015146, 2024). "It is necessary to explore whether NEDD4L could suppress tumor progression via targeting other ferroptosis core genes, such as GPX4, ASCL4 and FTH1." (PMID 39557844, 2024). "Furthermore, NEDD4L expression was negatively correlated with the survival outcomes, and was significantly reduced in advanced tumor stages." (PMID 39688910, 2024). "Interestingly, inhibition of NEDD4L led to destabilization of xCT, subsequent diminished the susceptibility of ESCC cells to ferroptosis and promoted tumor growth." (PMID 39557844, 2024). "Accumulating evidence has highlighted a role for NEDD4L as a tumor suppressor in CRC." (PMID 36831013, 2023). "Likewise, we also observed higher NEDD4L expression and lower tumor-cell proliferation (Ki67 staining) using immunohistochemistry (IHC)." (PMID 37240137, 2023). "Collectively, these findings revealed that NEDD4L may act as a tumor suppressor in ccRCC and participate in KSRP-modulated ccRCC progression." (PMID 37580757, 2023). "Since some substrates of NEDD4L are key factors in the signaling pathways that regulate tumor cell proliferation, the downregulation of these substrates by NEDD4L targeting might inhibit cell proliferation." (PMID 38027016, 2023). "In addition, NEDD4L is also found to protect tumor cells from undergoing ferroptosis by promoting the ubiquitin-mediated degradation of lactotransferrin (LTF)." (PMID 38174069, 2023). "In another study, NEDD4L targets the RSPO receptor LGR4/5 and DVL2 for degradation to inactivate the WNT/β-catenin signaling pathway and attenuate intestinal stem cell priming, leading to tumor predisposition and progression inhibition." (PMID 36831013, 2023).
tumor (continued). "Together, these results suggest that NEDD4L acted as a tumor suppressor gene in LUAD." (PMID 35090513, 2022). "Moreover, inactivation of NEDD4 and NEDD4L promotes Wnt activation, which improves tumor propensity and progression." (PMID 36293239, 2022). "NEDD4L expression was significantly decreased in tumour tissues compared with normal controls." (PMID 35646490, 2022). "The frequent down-regulation of NEDD4L in LUAD implies that NEDD4L might function as a tumour suppressor in LUAD." (PMID 35646490, 2022). "NEDD4L overexpression also inhibited tumor xenograft growth in vivo." (PMID 35646490, 2022). "Taken together, these findings suggested that NEDD4L might function as a tumor suppressor in clinical LUAD." (PMID 35090513, 2022). "Additionally, an in vivo study showed that knockdown of NEDD4L resulted in increased tumor growth and metastasis in nude mice (HCC827 LUC)." (PMID 36293239, 2022). "UBE2T was highly expressed in LUAD tumor tissues, in contrast, NEDD4L was lowly expressed." (PMID 34838005, 2021). "Since NEDD4L is downregulated and dysregulation of metabolism is involved in tumor progression, NEDD4L might be a potential therapeutic target in ccRCC." (PMID 34458018, 2021). "Also, decreased NEDD4L expression in NSCLC is found to be more tumor aggressive and can predict poorer survival time." (PMID 37305161, 2021). "Accordingly, Nedd4l displays a tumor suppressive function by suppressing the CTR1‐AKT signaling." (PMID 34278744, 2021). "Additionally, the concrete mechanisms have not been fully elucidated, although there are abundant studies proving that NEDD4L plays oncogenic or tumor-suppressive roles in cancers by modulating its substrates." (PMID 34869021, 2021). "Given that the oncoprotein functions of CTR1 are mainly dependent on AKT activation, our finding further demonstrates that the tumor suppressor function of Nedd4l is likely executed through governing the ubiquitination‐mediated degradation of CTR1 to dictate the downstream AKT signaling pathway." (PMID 34278744, 2021). "We analyzed the gene expression level of NEDD4L in pan-cancer from The Cancer Genome Atlas (TCGA) microarray data set, the correlation between gene expression and overall survival, disease-specific survival, and tumor immune microenvironment changes." (PMID 34539897, 2021). "Additionally, the tumor growth speed and weight tended to be significantly reduced in oe-NEDD4L+M2-EVs group and M2-EVs-anti miR-342-3p group vs. M2-EVs group (all p < 0.001)." (PMID 37305161, 2021). "In echoing this finding, depletion of either CTR1 or AKT1 both could compromise Nedd4l tumor suppressor roles in repressing cancer cell malignant phenotypes." (PMID 34278744, 2021). "NEDD4L may play a tumor suppressor effect in ccRCC, through tumor immune regulation and ubiquitination of key intracellular kinases." (PMID 34539897, 2021). "We found that increased tumor growth in vivo triggered by FLAG-UBE2T could be reversed by simultaneous transfection of HA-NEDD4L, due to overexpression of NEDD4L caused UBE2T reduction." (PMID 34838005, 2021). "Hence, all these findings provide experimental evidence for a model whereby Nedd4l exerts its tumor suppressor roles largely by inhibiting the CTR1‐AKT signaling pathway in a copper‐PDK1 binding dependent manner." (PMID 34278744, 2021). "Additionally, NEDD4L was found to suppress tumor metastasis by inhibiting the activity of TGF-β signaling pathway." (PMID 34458018, 2021). "The results of gene expression and tumor microenvironment analysis indicate that NEDD4L may be closely related to immune function." (PMID 34539897, 2021). "Quantitative PCR analysis showed that NEDD4L expression decreased in 82% of tumor tissues." (PMID 34539897, 2021). "NEDD4 has been reported as both tumour suppressor and oncogene, while the role of NEDD4L in cancer is largely unknown." (PMID 31867777, 2020).
tumor (continued). "We next investigated whether autophagy induction mediated by NEDD4L depletion would promote tumor growth in the in vivo mouse model." (PMID 31959741, 2020). "Here, we investigate novel roles of NEDD4L in modulating autophagy activity and mitochondrial metabolism on contributing to tumor progression by which regulates the protein levels of an autophagy protein, ULK1, and ASCT2, a transporter of glutamine that is a substrate for mitochondrial anaplerosis." (PMID 31959741, 2020). "Similarly, based on Q-PCR, we also detected that the transcript level of NEDD4L in the 131 tumor tissues from CRC patients in our hospital was substantially (P < 0.001) lower than that in the 30 normal tissues." (PMID 33117809, 2020). "Unlike the previous report showing that Nedd4‐deficient tumour phenotype requires surrounding microenvironment, our results show that deletion of Nedd4/Nedd4l in the intestinal epithelium alone is sufficient to enhance Apcmin tumour growth with significant increase in ISC numbers." (PMID 31867777, 2020). "Interestingly, the levels of either ULK1 or LC3B increased, as the intensity of NEDD4L staining decreased in the same tumor regions." (PMID 31959741, 2020). "The downregulation of NEDD4L can also promote tumor growth and inhibit the MAPK/ERK signal pathway." (PMID 31775867, 2019). "Moreover, diverse clonal populations within ESCC tumours and how this diversity might affect the sensitivity of tumour cells to NEDD4L/KLF5 axis inhibition." (PMID 39317954, 2024). "Moreover, NEDD4L has been shown to be involved in both oncogenesis and tumor suppression." (PMID 38664594, 2024). "Similar to previous reports, our study revealed that NEDD4L was downregulated and RAC2 was upregulated in ccRCC tissues, and low expression of NEDD4L and high expression of RAC2 were both associated with poor prognosis, shorter survival, higher tumor–node–metastasis stage, and worse G grade." (PMID 39596003, 2024). "However, whether NEDD4L is directly involved in the inhibition of EMT in tumor cells warrants further study." (PMID 38027016, 2023). "Thus, NEDD4L mainly inhibits the migration and invasion of human tumor cells." (PMID 38027016, 2023). "Therefore, the miRNA-mediated targeting of NEDD4L consequently resulted in tumor progression." (PMID 37568787, 2023). "Furthermore, the role of NEDD4L in tumour growth in vivo was examined." (PMID 35646490, 2022). "The expression of NEDD4L in the data of TCGA pan-cancer species, its correlation with patient survival, the main function of genes, and whether it will affect the tumor immune microenvironment and other issues are in this paper through TCGA data analysis to draw conclusions." (PMID 34539897, 2021). "Consequently, NEDD4L might act as a tumor-suppressor gene to repress the malignant biological behavior of HCC, while the relationship between NEDD4L and the Wnt/β-catenin signaling pathway needs further investigation to prove." (PMID 34869021, 2021). "To this end, we observed that depletion of NEDD4L in cancer cells could markedly induce colony formation and anchorage‐independent growth in different cancer types, and tumor growth in xenograft mouse models." (PMID 34278744, 2021). "All these results together suggested that NEDD4L may play a tumor suppressive role in AML biology." (PMID 34809620, 2021). "However, NEDD4L might exert a tumor-promoting effect, and the expression of NEDD4L was downregulated by DNA damage-binding protein 2 (DDB2)." (PMID 34869021, 2021). "We also detected a high transcriptional level of NEDD4L in CRC tumor tissues and found that its overexpression in CRC cells could promote cellular apoptosis, suppress the glycolytic process, influence the expression of key proteins, and modulate the p-AKT protein level." (PMID 33117809, 2020). "Therefore, NEDD4L has been identified as having a tumor suppressor role." (PMID 33282879, 2020).
tumor (continued). "Indeed, expression of NEDD4L was profoundly downregulated in CRCs, suggesting that inhibition of the tumour suppressors NEDD4/NEDD4L may be an alternative Wnt activating mechanism for some CRCs." (PMID 31867777, 2020). "Therefore, NEDD4L may be considered a tumor suppressor, although, this needs to be verified through direct and robust experimental evidence." (PMID 31673244, 2019). "Therefore, we propose that NEDD4L may act as a tumor suppressor in CRC by inhibiting canonical WNT signaling." (PMID 24312311, 2013). "BRMS1L, CPEB3, KIF3B, NEDD4L, PTPRJ, and RBL2 were significantly downregulated in tumor samples compared to controls." (PMID 40943553, 2025). "Of those, eight (HOXA3, HOXA5, ATP10A, SOX2, MIR922, ADAMTSL1, KHDRBS2, and LITD1) were hypermethylated in at least one LS tumor group like here in FAP normal, whereas NEDD4L, and FOXP1 were hypermethylated in LS carcinomas and here in LS normal." (PMID 40753397, 2025). "NEDD4L, which belongs to the E3 ubiquitin ligase NEDD4 family, is related to tumor genesis, metastasis and drug resistance." (PMID 38831335, 2024). "According to The Cancer Genome Atlas and GEO data, the NEDD4L gene was significantly downregulated in tumor tissues of patients with CRC and in tumor tissues from CAC mice compared with their normal tissues." (PMID 39688910, 2024). "Tumour formation under irradiation in vivo was simulated after the sh‐NEDD4L and sh‐KLF5 were delivered to the mice, showing that NEDD4L inhibition accelerated the rate of ESCC tumour generation, while KLF5 inhibition conversely suppressed tumour growth." (PMID 39317954, 2024). "Silenced NEDD4L facilitated ESCC cell proliferation, migration and invasion and inhibited apoptosis in vitro, and accelerated tumour growth in vivo, while KLF5 inhibition produced an opposite effect." (PMID 39317954, 2024). "NEDD4L was low expressed in human ESCC samples, silencing NEDD4L inhibited ferroptosis by stabilizing xCT, resulting in tumor growth promotion in xenograft mice models." (PMID 39557844, 2024). "NEDD4L contributes to the ubiquitination degradation of GPX4, induces the ferroptosis in non-small cell lung cancer, and thereby suppresses tumor progression." (PMID 38831335, 2024). "Evidences show the implicated mechanism of NEDD4L in both solid and non-solid tumors, which is involved in a range of pathophysiological processes, indicating that NEDD4L plays an anti-tumor effect in variety aspects referring tumor microenvironment and metabolism." (PMID 38027016, 2023). "Consistently, the protein expression of P-AMPK and NEDD4L were elevated in NCI-H1975 and SPCA1 tumor samples upon JAC4 treatment." (PMID 37240137, 2023). "Therefore, NEDD4L may inhibit tumor growth by regulating the cell cycle." (PMID 38027016, 2023). "Then the biological role of NEDD4L in regulating LUAD cell proliferation was examined using CCK-8 and colony formation assay in vitro, and mouse xenograft tumor model in vivo." (PMID 35646490, 2022). "In the present study, to define the role of NEDD4L in LUAD, the NEDD4L expression in LUAD was analysed in TCGA database and validated in tumour tissues." (PMID 35646490, 2022). "The biological function of NEDD4L on regulating LUAD cell proliferation was tested with Cell Counting Kit-8 (CCK-8) assay in vitro, and mouse xenograft tumor model in vivo." (PMID 35646490, 2022). "Our group first identified NEDD4L as a novel tumor suppressor gene in MM and, by analysis of an Affymetrix HTA 2.0 array, found that NEDD4L is expressed at low levels in Bor-resistant MM cells." (PMID 35236820, 2022). "GSEA gene function enrichment analysis results suggest that NEDD4L participates in tumor immune regulation in KIRC, and affects tumor cell growth and apoptosis." (PMID 34539897, 2021). "This is in agreement with previous studies showing that miR-21 and miR-27a acted as cooperative repressors of a network of tumor suppressor genes that included PDCD4, BTG2, and NEDD4L." (PMID 34208765, 2021).
tumor (continued). "NEDD4L modulated the degradation of copper transporter 1 (CTR1) in ubiquitination and exerted tumor inhibition through the CTR1-Akt signaling pathway." (PMID 34869021, 2021). "In addition, we also determined the potential role of NEDD4L in AML by further functional study validation, and showed the anti-proliferative and pro-apoptotic effects of NEDD4L in leukemic cell line K562, which suggested that NEDD4L may play a tumor suppressive role in AML biology." (PMID 34809620, 2021). "NEDD4L blocks iron accumulation and cell oxidative damage by mediating LTF degradation and ultimately inhibiting tumour growth." (PMID 34503532, 2021). "More interestingly, the protein levels of NEDD4L and ULK1 or ASCT2 were inversely expressed in both xenograft tumor and tumor from spontaneous PDAC mouse model, KPC mice." (PMID 31959741, 2020). "The induction of JP1 on NEDD4L was further confirmed in both B16F10 cells allograft and metastatic tumor tissues by Immunoblotting and IHC assay." (PMID 32724456, 2020). "We propose a novel mechanism showing that cancers expressing low levels of NEDD4L enhance autophagy and mitochondrial metabolism via deregulating the protein activity of ULK1 and a glutamine transporter, and so promote tumor development." (PMID 31959741, 2020). "In contrast, NEDD4L mRNA, the closest homolog to NEDD4, was the most highly downregulated family member, and was significantly downregulated in all tumor stages." (PMID 24312311, 2013). "Moreover, the gene and protein levels of NEDD4L were significantly downregulated on the 90th day after the AOM/DSS induction, when the mice had obvious neoplasia formation." (PMID 39688910, 2024). "However, it is unclear if a specific AS isoform of NEDD4L is responsible for regulating TGFβ signaling in TNBC tumors, where it has the potential to drive multiple aspects of tumor progression." (PMID 38664594, 2024). "Overexpression of NEDD4L showed a trend of increased growth at the endpoint, although the difference in tumor growth was not statistically significant." (PMID 38213996, 2024). "Moreover, the expression of both JWA and NEDD4L was increased; however, EGFR, p-EGFR, p-AKT, and p-STAT3 expression levels were reduced in JAC4-treated tumor tissues compared to those in the control group." (PMID 37240137, 2023). "Furthermore, NEDD4L has been proved to act as a tumor suppressor through regulating EGFR, TGFβ, and Wnt signaling pathways, and the lower NEDD4L level showed poor prognosis in a variety of cancers clinically." (PMID 37495186, 2023). "A study highlighted NEDD4 as an invasion-associated molecule in gallbladder carcinoma and demonstrated that at the transcriptional level NEDD4L regulates MMP-1 (Matrix metalloproteinase-1) and MMP-13 expression, which is overexpressed at an early stage of tumor invasion in various malignant tumors." (PMID 36293239, 2022). "For example, NEDD4L prevents autophagy activity under metabolic stress by destabilizing ULK1, an autophagy protein, and ASCT2, a glutamine transporter, hence reducing mitochondrial functioning and tumor suppression." (PMID 36293239, 2022). "In this study, we identified Nedd4l as one of the upstream physiological E3 ligases for CTR1, and depletion of NEDD4L could significantly enhance CTR1 protein levels and lead to tumor growth both in cells and xenografted mouse models." (PMID 34278744, 2021). "NEDD4L belongs to the NEDD4 family of the E3 HECT domain ubiquitin ligases and has been suggested to regulate several signaling pathways, thus acting as a tumor suppressor in several cancers." (PMID 33846348, 2021). "In RCC cells, M2-EV-derived miR-342-3p could specifically bind to NEDD4L and consequently elevate CEP55 protein expression via suppressing NEDD4L, thereby exerting tumor-promoting effects." (PMID 37305161, 2021).